PRL (prolactin)
Diseases named in the same sentence as PRL in open-access papers (continued):
Sharing a sentence is not in itself a finding about the gene and the disease.
adenoma (continued). "Significant predictors of DA resistance have been identified as male gender, large adenomas, and prolonged time to prolactin (PRL) normalization." (PMID 34054739, 2021). "It was treated medically with cabergoline and a repeat pituitary MRI after eight weeks of initiating treatment showed a 4-mm reduction in the size of the adenoma, and prolactin level decreased to 6,794 miu/L." (PMID 35070533, 2021). "The patient has had transsphenoidal pituitary adenomectomy with histology confirming a thyrotropin-prolactin-secreting adenoma." (PMID 34888106, 2021). "Prolactin-secreting adenomas represent the most predominant type of all PitNET and for this subtype of tumors, the medical therapy relies on the use of dopamine agonists (DAs)." (PMID 35095761, 2021). "A recent study evaluated this MRI feature in other functioning adenomas and found that T2-hypointensity in female prolactinomas was related to younger age at diagnosis, higher baseline prolactin (PRL) levels, and dopamine agonist resistance." (PMID 34636742, 2021). "In contrast to other secreting adenomas, normalization of PRL levels was the only criterion used by all studies to define the success of GK." (PMID 34638482, 2021). "For instance, RPSAP52, an antisense lncRNA from the HMGA2 locus, has been found to be overexpressed in both gonadotroph- and prolactin-producing adenomas of this gland, where its expression has been correlated with the expression of HMGA2." (PMID 34885097, 2021). "This is also consistent with the lower EER and DER in GH-producing adenomas than in PRL-producing adenomas and NF adenomas." (PMID 33881731, 2021). "In 2012, Mulligan and colleagues demonstrated improved adenoma lateralization using a prolactin-adjusted intersinus ACTH gradient of > 1.4 in their series." (PMID 33811521, 2021). "In case of large or invasive adenomas, postoperative symptoms-mass or increased PRL levels arises from tumor remnants: high-dose CAB treatment is required, with increased risk of side-effects." (PMID 34173929, 2021). "The T2 signal intensity ratio was significantly lower among GH-producing adenomas than among NF adenomas (P < 0.001); and was also significantly lower in GH-producing adenomas compared to PRL-producing adenomas (P < 0.001)." (PMID 33881731, 2021). "Dual staining adenomas are identified when prolactin expression is present in a higher percentage of cells (more than 5%) than pure single staining adenomas, but there is uncertainty in practice due to the semi-quantitative nature of IHC method." (PMID 34530798, 2021). "Pituitary prolactin (PRL)-secreting adenomas have the highest vascular densities, and growth hormone (GH)-producing adenomas have the lowest vascular densities." (PMID 34869016, 2021). "In our cohort, the addition of octreotide LAR to CAB resulted in a significant response in terms of PRL levels and adenoma size, as recently reported; however, the development of liver function abnormalities resulted in somatostatin analog discontinuation." (PMID 34173929, 2021). "Seventy-one patients were assessed for granulation patterns and prolactin co-expression as dual staining adenomas." (PMID 34530798, 2021). "PD-L1 expression was found in both functioning and non-functioning pituitary tumors, with higher levels in functioning (GH- and PRL-expressing) adenomas, while tumor-infiltrating lymphocytes were also observed and correlated with PD-L1 expression." (PMID 33112279, 2021). "Although SST5 expression was negative, he was started on octreotide LAR 30 mg monthly in an attempt to stabilize PRL levels, but PRL remained elevated and adenoma size increased." (PMID 34867776, 2021).
adenoma (continued). "It has been previously reported in the first case report that testosterone replacement therapy can promote a rise in PRL levels or adenoma growth (via the aromatization to estradiol)." (PMID 34173929, 2021). "Baseline PRL levels were extremely high (55,440 μg/L) and dropped only partially after surgery (33,000 μg/L), with a large residual adenoma (52 × 48x50mm)." (PMID 34173929, 2021). "Further, two out of 12 cases showed a combination of a GH/prolactin/TSH adenoma with a null-cell adenoma." (PMID 34478014, 2021). "Therapy with DA aims to reduce levels of PRL and, in the case of adenoma, to induce tumor shrinkage." (PMID 33314003, 2021). "For a PRL cut-off value of 204 μg/L (4338 mU/L), both sensitivity and specificity of diagnosing a macro adenoma were optimal." (PMID 33963239, 2021). "The EER was significantly lower in GH-producing adenomas than in PRL-producing adenomas, NF adenomas, and other adenomas (P < 0.001, P < 0.001, and P = 0.004, respectively)." (PMID 33881731, 2021). "In our study, which includes only pure PRL-secreting adenoma, the average PRL level was significantly higher in the macroprolactinoma group than in the microprolactinoma group (516 vs. 114 ng/mL)." (PMID 32849307, 2020). "The reason for normalization of PRL levels is unclear, but this phenomenon is more likely to occur in mixed adenomas." (PMID 32733382, 2020). "They usually are somatotropinomas or mixed GH and prolactin secreting adenomas and this secretory profile, combined with the young age at onset (childhood and adolescence) means that AIP mutations are the most frequent known cause of pituitary gigantism." (PMID 32604740, 2020). "The PD-L1 RNA transcript is significantly increased not only in GH-secreting and PRL-secreting adenomas compared to null cell and silent gonadotroph adenomas but also in primary pituitary tumors compared to recurrent tumors." (PMID 33362722, 2020). "He underwent surgical therapy with transsphenoidal surgery which showed an adenoma with most tumor cells staining positive for GH and prolactin." (PMID 32311048, 2020). "Thyroid function and PRL levels normalized, suggesting a TSH/PRL cosecreting macroadenoma, while the dimension of the adenoma showed only a small change over 5-years of follow-up (12 and 10 mm in 2012 and 2017, respectively)." (PMID 32733382, 2020). "Prolactin (PRL) secreting adenomas are particular in the responsiveness to a pharmacological therapy in contrast to other pituitary tumours." (PMID 32429916, 2020). "As regards the pituitary, prolactin-secreting adenomas can be induced in animals by prolonged oestrogen treatment and prevented by oestrogen receptor agonists." (PMID 32183012, 2020). "The other thirteen patients who carried prolactin secreting adenomas were prescribed with dopamine agonist and were recommended for outpatient follow-up regularly." (PMID 32546762, 2020). "In mice with and without multiple endocrine neoplasia 1 (MEN1), anti-VEGF therapy reduces tumor size, prolactin secretion, and vascularity in prolactin-secreting adenomas as well as normalizing blood vessels and reducing intra-tumoral hemorrhage." (PMID 32012988, 2020). "Dopamine agonists, in particular, cabergoline (CBG), are the first-choice treatment, aiming to lower prolactin levels (PRL), reduce adenoma size, and restore gonadal function." (PMID 31001736, 2019). "In children, depending on the study population, ACTH- and PRL-secreting adenomas are the most commonly encountered subtypes." (PMID 31877737, 2019). "Ten (18.2%) of the adenomas displayed both GH and PRL expression while the remaining 45 were pure GH‐producing tumours." (PMID 30843342, 2019). "PRL-PA occasionally express GH, and most importantly, all Cluster 1 adenomas can be differentially defined by pituitary-specific transcription factor 1 (Pit-1)." (PMID 31455412, 2019).
adenoma (continued). "PRL expression is also seen by immunohistochemistry in pluri-hormonal Pit-1 adenomas, mammosomatotroph adenomas, and mixed somatotroph-lactotroph adenomas." (PMID 31847209, 2019). "Patients with AIP mutations commonly present with GH-secreting adenomas; the second most common presentation is that of GH/PRL co-secreting adenomas." (PMID 31877737, 2019). "Prolactin secreting adenomas can be part of genetic syndromes, such as multiple endocrine neoplasia type 1 (MEN1) or type 4 (MEN4), familial isolated pituitary adenoma (FIPA) or Carney complex." (PMID 31847209, 2019). "PRL‐secreting adenomas are monoclonal in nature, supporting the theory that a spontaneous somatic mutation is the primary pathogenetic mechanism in this disorder (Herman, Fagin, Gonsky, Kovacs, & Melmed, 1990)." (PMID 31692290, 2019). "Other than prolactin-secreting adenomas (PRL-omas), which should first be treated with dopamine agonists (DAs), the primary treatment option is usually surgery." (PMID 31191457, 2019). "For patients with PRL-omas, DAs such as bromocriptine or cabergoline are the primary treatment and achieve successful treatment of these adenomas." (PMID 31191457, 2019). "As expected, GH-PA, GH-PRL-PA, and PRL-PA formed a subclass, showing a close relationship among these three subtypes of adenomas." (PMID 31455412, 2019). "The identification of estrogen metabolites and 17-ketosteroids in the urine of patients with PRL-secreting adenomas is most likely to be due to decreased activity of 3 beta-hydroxysteroid dehydrogenase and 5α-reductase that occurs among these patients." (PMID 30705668, 2018). "ERK1/2 activation plays an important role in the proliferation of PRL-secreting adenomas and in PRL secretion by the pituitary gland." (PMID 29622766, 2018). "An immunohistochemical analysis revealed that OMP was expressed in PRL-secreting cells of normal human pituitary tissue, but was almost undetectable in adenoma tissue." (PMID 29622766, 2018). "The results of the present study demonstrated that tumor size, preoperative PRL levels, and invasion of adenomas are independent factors that affect the therapeutic outcomes of patient postsurgery." (PMID 30407358, 2018). "To confirm the regulation of PRL by OMP in the human pituitary, we analyzed OMP expression in normal pituitary and PRL-secreting adenoma (prolactinoma) tissue samples by western blotting." (PMID 29622766, 2018). "In the PRL <100 ng/mL group, there were a large number of giant adenomas and invasive prolactin adenomas, which affected the postoperative remission rate." (PMID 30407358, 2018). "The results of this study demonstrated that tumor size, preoperative PRL levels, and invasion of adenomas represent independent factors that can affect the success of surgery." (PMID 30407358, 2018). "The PRL levels were lower than most prolactinomas for some patients with macroadenomas and large adenomas." (PMID 30407358, 2018). "Fourteen (19%) of the adenomas displayed both GH expression and PRL expression, while the remaining were pure GH‐producing adenomas." (PMID 29266696, 2018). "Signs and symptoms are principally due to macro-adenomas compressing cerebral structures, or specifically derived by the over-production of one or more pituitary hormones (i.e prolactin, PRL; somatotropin, GH; and corticotropin, ACTH)." (PMID 30428914, 2018). "GH levels were significantly decreased at postoperative day 7 in patients with other types (TSH-, PRL-, and LH-secreting) or null-cell type of adenoma (P<0.05)." (PMID 29108291, 2017). "Immunohistochemically, 15 (42.9%) adenomas expressed GH alone, 14 (40%) expressed both GH and prolactin, and the remaining adenomas expressed GH and other hormones." (PMID 29267504, 2017). "Following long-acting somatostatin analogue treatment, she underwent transsphenoidal surgery (GH- and prolactin-positive adenoma, Ki-67 <1%) with normalization of GH, prolactin and IGF-1." (PMID 28973408, 2017).
adenoma (continued). "Magnetic resonance image (MRI) results and serum PRL levels were consistent with the diagnosis of PRL-secreting adenomas." (PMID 29245312, 2017). "Instead, effective medical therapy has been demonstrated in functioning adenomas, in particular in prolactin and growth hormone secreting pituitary tumors." (PMID 28915655, 2017). "As prolactin was elevated and brain MRI showed a suspected 3 mm adenoma, treatment with Parlodel was initiated." (PMID 29231814, 2017). "Arg9Gln variant has been identified in 3 unrelated young sporadic patients affected by GH, prolactin and ACTH-secreting adenomas respectively, the latter being a condition rarely associated with AIP mutations." (PMID 29036195, 2017). "GeneChip microarrays and proteomics analyses demonstrated increased expression of NOTCH3 in non functioning and prolactin secreting adenomas in humans while in somatotropinomas a significantly reduced expression of NOTCH3 was found." (PMID 28915655, 2017). "Patient’s evolution under dopaminergic treatment was marked by the recovery, for a transitional period, of mestrual cycles and the occurrence of hot flushes, normalization of prolactin levels and reduction of adenoma size." (PMID 28904704, 2017). "It should be stressed that plurihormonal adenomas often secrete GH, prolactin and ACTH simultaneously or a combination of one of these hormones and TSH." (PMID 28418929, 2017). "Normal PRL levels and sustained reduction or disappearance of adenomas were achieved in most of patients, probably due to the decrease of estrogen levels." (PMID 26909481, 2016). "Nonetheless, in the setting of MPA, PRL-secreting tumors were the most common incidental lesion coexisting with ACTH-secreting adenomas, which potentially points toward a genetic common background." (PMID 26869991, 2016). "A dose-dependent inhibition of PRL secretion occurred in three mixed GH/PRL adenomas under PEG with a maximum of 52.8±11.5% at 10μg/mL (P<0.0001 vs control)." (PMID 27267119, 2016). "Calcification is frequently detected in prolactin-secreting adenomas (10–15%) but is less frequently detected in growth hormone-secreting adenomas." (PMID 27917338, 2016). "Among the component tumors, prolactin (PRL)-immunopositive adenomas are highly prevalent, albeit mute in the majority of cases." (PMID 26869991, 2016). "Isolated case reports evoke Cushing’s disease patients in whom the surgeon removed a PRL- or GH-secreting adenoma while the ACTH-secreting tumor was identified and resected at reoperation." (PMID 26869991, 2016). "In 3 patients, who were diagnosed with mixed GH and PRL secreting adenomas, Pegvisomant and Bromocriptine treatment was established." (PMID 27453753, 2016). "The clinical and pathologic characteristics of aggressive prolactin-secreting adenomas are reviewed, as well as their response to dopamine agonists, surgery, radiotherapy, and chemotherapy." (PMID 27489751, 2016). "We also evaluated the postoperative hormonal remission rate of GH, PRL or ACTH secreting adenomas, respectively." (PMID 27124276, 2016). "Evaluation of multiple adenomas in autopsy materials most commonly demonstrated immune-positivity for PRL; however, tumors staining for PRL are rather mute in the setting of MPA." (PMID 26869991, 2016). "Silent cell PRL-secreting adenomas or functional prolactinomas coexist, most frequently, with either GH- or ACTH-secreting tumors." (PMID 26869991, 2016). "One of these previously reported adenomas was made of cells storing both GH and PRL reflecting probably a silent somatoprolactinoma." (PMID 26106585, 2015). "The data from recent literatures showed that the hormone control was higher for PRL secreting adenomas than that for GH secreting adenomas, and higher in microadenoma than macroadenoma." (PMID 25270611, 2015). "Second in frequency are the tumors of the anterior pituitary that include adenomas producing prolactin, growth hormone, thyroid-stimulant hormone, adrenocorticotropic hormone, and nonfunctioning tumors." (PMID 26161274, 2015).
adenoma (continued). "Four of the patients with macroadenomas had surgery, and the histopathological study confirmed GH- or GH/PRL-positive adenomas." (PMID 26186299, 2015). "In general, all patients harboring macroprolactinomas should be treated, the objectives being to achieve normal or near normal PRL levels, to reduce or stabilize adenoma size and to recover altered pituitary axes." (PMID 28702224, 2015). "If Ezzat and coworkers reported a high variability of PRL-secreting adenomas percentage between 25 and 41% of cases, our study reported a variability ranged between 10% (found in group 2) and 23% (for group 1)." (PMID 26078755, 2015). "Our case highlights the difficulty in definitively diagnosing an unusual prolactin-producing adenoma based on histopathology alone and the importance of referring to clinical information and immunohistochemical findings when deriving the diagnosis." (PMID 26228535, 2015). "Adenoma shrinkage is considered an inferior parameter for CAB resistance due to the limited data in the literature regarding the correlation with PRL control." (PMID 28702224, 2015). "Regarding PRL-secreting adenomas, both groups 1 and 2 had a lower number of cases compared with previous similar populational studies." (PMID 26078755, 2015). "Somatotroph axis evaluation is limited in patients with PRL-secreting tumors, due to the possibility of GH and PRL co-secretion in 10 % of these adenomas." (PMID 28702224, 2015). "Three patients of four GH producing adenomas showed normalization of GH secretion, and in the patient with PRL producing adenoma the level of PRL decreased to 33.5 ng/mL." (PMID 26339240, 2015). "The treatment objectives for patients harboring macroprolactinomas are to achieve normal or near normal prolactin (PRL) levels, to reduce or stabilize adenoma size and to recover altered pituitary axes." (PMID 28702224, 2015). "Prolactin-secreting adenomas were reported in the context of the Familial Isolated Pituitary Adenoma (FIPA) syndrome linked to AIP gene mutation, although it is usually associated with acromegaly." (PMID 28702224, 2015). "Among patients with macroprolactinomas, the presence of both low PRL levels and adenoma disappearance provided 67 % assurance for permanent or very long-standing remission, compared with only 22 % assurance for patients with a visible remnant on MRI." (PMID 28702224, 2015). "We present a case of a 21 year old male patient diagnosed with a 2.2 cm prolactin-secreting adenoma in contact with the optic chiasm." (PMID 25165538, 2014). "In PRL-secreting adenomas, serum PRL level was strongly correlated with adenoma volume (r = 0.9679, P < 0.001)." (PMID 25431591, 2014). "These include dimorphous adenomas composed of GH and prolactin cells, monomorphous mammosomatotrope adenomas (which produce both GH and prolactin), and rarely primitive and often aggressive acidophil stem-cell adenomas." (PMID 25298881, 2014). "The CD + PRL group also had a tendency for higher Knosp grades so the adenoma was more likely to have invaded the cavernous sinus space." (PMID 25506361, 2014). "Meanwhile, the effect of somatostatin analog treatment on vessel diameter in PRL-secreting adenomas would be interesting to investigate in the future." (PMID 25431591, 2014). "The agents act by binding to specific dopamine receptors on the prolactin-secreting cells, resulting in reduced synthesis and secretion of prolactin, and adenoma cell size." (PMID 25142896, 2014). "PRL-secreting adenomas had significantly larger perimeter and vessel diameter than nonfunctioning and GH-secreting adenomas." (PMID 25431591, 2014). "Although there are reports of reversibility of valvulopathy with other DAs19, this is the first case of reversal of valvular abnormalities after stopping cabergoline treatment in a patient with a prolactin-secreting adenoma." (PMID 25165538, 2014).